FBXO44 (F-box protein 44)
Description:
Substrate-recognition component of two distinct E3 ligase complexes, the SKP1-CUL1-FBXO44 complex and the CUL4B-DDB1-FBXO44 complex. The complex SCF(FBXO44) complex ubiquitinates and mediates BRCA1 degradation. In association with cullin 4B/CUL4B and DDB1, mediates the ubiquitination of RGS2 leading to its degradation. Additionally, regulates the pregnane X receptor/NR1I2 protein level by ubiquitination and degradation.
Synonyms: FBG3; FBX30; FBX44; FBX6A; FBXO6A; MGC14140
Tractability: No criterion of Open Targets' tractability assessment is met for any kind of drug.
Gene: Protein-coding gene on chromosome 1 (11,650,618 to 11,663,327, forward strand). Ensembl gene ENSG00000132879.
Subcellular location: Nucleus
Subcellular location (Human Protein Atlas): Nucleoplasm
Pathways (Reactome):
Immune System: Antigen processing: Ubiquitination & Proteasome degradation
Metabolism of proteins: Neddylation
Gene Ontology:
Molecular function: protein binding; ubiquitin-like ligase-substrate adaptor activity; ubiquitin protein ligase activity
Biological process: proteasomal protein catabolic process; proteasome-mediated ubiquitin-dependent protein catabolic process; ERAD pathway; glycoprotein catabolic process; SCF-dependent proteasomal ubiquitin-dependent protein catabolic process
Cellular component: nucleus; SCF ubiquitin ligase complex; cytoplasm; cytosol
Genetic constraint (gnomAD): Loss-of-function variants: 25 observed, 35.42 expected, observed/expected ratio (o/e) 0.71, 90% interval 0.51 to 0.99. The upper end of that interval is the gene's LOEUF score, 0.99, which puts it in group 4 of 6, group 1 being the genes least tolerant of losing a copy. Missense variants: 311 observed, 357.69 expected, observed/expected ratio (o/e) 0.87, 90% interval 0.79 to 0.95. Synonymous variants: 147 observed, 159.53 expected, observed/expected ratio (o/e) 0.92, 90% interval 0.81 to 1.06.
Homologues: Orthologues: chimpanzee FBXO44 (100% identical), macaque FBXO44 (100% identical), dog FBXO44 (98% identical), mouse Fbxo44 (96% identical), rat Fbxo44 (96% identical), guinea pig FBXO44 (95% identical), tropical clawed frog FBXO44 (52% identical), zebrafish fbxo6.3 (44% identical), zebrafish fbxo44.1 (43% identical), zebrafish fbxo44.3 (42% identical), zebrafish fbxo44.5 (42% identical), zebrafish fbxo6.1 (36% identical), and 5 more. Paralogues in human: FBXO6 (75% identical), FBXO2 (48% identical), FBXO27 (38% identical), FBXO17 (34% identical), NCCRP1 (25% identical).
Diseases named in the same sentence as FBXO44 in open-access papers:
FBXO44 is named in the same sentence as 10 diseases in open-access papers, as found by Europe PMC text mining. Sharing a sentence is not in itself a finding about the gene and the disease. The quoted sentences say what the papers report.
colon cancer (2 papers, 2022 to 2023). "F-Box protein 44 (FBXO44) has been identified as an essential repressor of REs in a panel of cancer cells, including colon cancer cell lines." (PMID 34385592, 2022). "FBXO44 showed upregulation in colon cancer but showed no significant expression change in stomach cancer." (PMID 36774361, 2023).
colorectal cancer (1 paper, 2025). A primary or metastatic malignant neoplasm that affects the colon or rectum. "This study reveals a phosphorylation‐dependent mechanism involving AURKA and highlights the FBXO44/FOXP1/Cyclin E2 axis as a potential therapeutic target in colorectal cancer." (PMID 41051444, 2025). "To elucidate the role of FBXO44 in colorectal cancer (CRC) progression, we first examined its expression profile." (PMID 41051444, 2025). "We further explored the functional significance of FBXO44‐mediated FOXP1 regulation on the phenotype of colorectal cancer." (PMID 41051444, 2025). "FBXO44 promotes colorectal cancer progression by targeting FOXP1 for ubiquitin‐mediated degradation." (PMID 41051444, 2025). "This study identifies F‐box only protein 44 (FBXO44) as an oncogene in colorectal cancer (CRC)." (PMID 41051444, 2025).
dementia (1 paper, 2025). Loss of intellectual abilities interfering with an individual's social and occupational functions. "Our pharmacogenomic analysis identifies TRIM2, FBXO44, and GLTPD2 as potential genetic modifiers, whose higher expression levels attenuate the deleterious effects of N06AX antidepressants on WMH burden, with GLTPD2 also reducing dementia risk." (PMID 40799764, 2025).
Hypertension (1 paper, 2022). The presence of chronic increased pressure in the systemic arterial system. "Another example is the CUL4B•DDB1•FBXO44-dependent ubiquitination of RGS2 (regulator of G protein signaling 2), a protein that regulates vasoconstriction and the lack of which leads to hypertension in mice." (PMID 35327608, 2022).
cancer (6 papers, 2021 to 2025). A tumor composed of atypical neoplastic, often pleomorphic cells that invade other tissues. "Immunohistochemical analysis and in silico evaluation of cancer patient databases showed FBXO44 is frequently overexpressed and correlated with poor prognosis in several major cancer types, including breast, lung, gastric, and ovarian cancers." (PMID 33681705, 2021). "FBXO44 inhibition also promoted DSBs and genomic instability in cancer cells, as indicated by cGAS+ γH2AX+ micronuclei." (PMID 33681705, 2021). "Fbxo44 is a key regulator in H3K9me3-mediated cancer cells and may induce replication stress and DNA double-strand breaks in cancer cells by stimulating the antiviral pathway and the interferon (IFN) signaling pathways." (PMID 39511641, 2024). "FBXO44 inhibition reactivates REs, leading to IFNγ signaling activation in cancer cells, as shown by the increased expression of IFNGR1, IFNGR2, and other ISGs and the decreased expression of protein tyrosine phosphatase nonreceptor type 2 (PTPN2), an IFNγ signaling inhibitor." (PMID 34385592, 2022). "Therefore, FBXO44/SUV39H1 inhibition can enhance cancer cell immunogenicity and overcome ICB resistance via the transcriptional regulation of IFNγ signaling." (PMID 34385592, 2022). "In our recent study, we reported that the F-box protein FBXO44 plays an essential role in H3K9me3-mediated transcriptional silencing of REs in cancer cells and this process could provide a therapeutic opportunity for cancer treatment." (PMID 33681705, 2021). "Finally, we generated an immune gene signature related to FBXO44 targeting and demonstrated its ability to predict immunotherapy response in cancer patients." (PMID 33681705, 2021). "FBXO44/SUV39H1 are crucial repressors of RE transcription, and their inhibition selectively induces DNA replication stress and viral mimicry in cancer cells." (PMID 39199304, 2024). "FBXO44 recruits SUV39H1 to REs, which is essential for H3K9me3-mediated transcriptional silencing of REs in cancer cells." (PMID 34385592, 2022). "Functional targeting of FBXO44/SUV39H1 induced DNA replication stress and viral mimicry selectively in cancer cells, leading to inhibition of tumor growth and enhanced anti-PD-1 therapy response in preclinical mouse models." (PMID 33681705, 2021). "In summary, our study reported that FBXO44 recruits SUV39H1, CRL4RBBP4/7, and Mi-2/NuRD to form a repressive epigenetic complex at the replication fork that promotes H3K9me3-mediated RE silencing post-DNA replication in cancer cells." (PMID 33681705, 2021). "Inhibition of FBXO44 or its co-factor SUV39H1 stimulated antiviral pathways and interferon (IFN) signaling and induced replication stress and DNA double-strand breaks (DSBs) in cancer cells, leading to restricted tumor growth and synergy with anti-PD-1 therapy." (PMID 33681705, 2021). "Additionally, FBXO44 (10-fold change, FDR = 0.00040) is a gene known to promote DNA replication-coupled repetitive element silencing and inversely correlate with replication stress in cancer cells, potentially representing an adaptive response that could contribute to SN-38 resistance." (PMID 41280668, 2025).
tumor (4 papers, 2021 to 2025). "We analyzed the correlation between FBXO44 mRNA expression and clinical pathological features (cohort 1), finding significant positive associations with tumor size, T stage, and vascular invasion." (PMID 41051444, 2025). "Additionally, xenograft tumor models indicated that FOXP1 deficiency reversed the suppression of subcutaneous tumor growth in nude mice induced by FBXO44 knockdown, and vice versa." (PMID 41051444, 2025). "In our cohort of 80 paired CRC samples (cohort 1), FBXO44 mRNA levels were significantly elevated in tumor tissues." (PMID 41051444, 2025). "In conclusion, our analysis revealed that a high level of FBXO44 expression is associated with a poor prognosis in AEG patients and promotes the growth and metastasis of AEG tumor cells in vitro and in vivo." (PMID 36774361, 2023). "The FBXO44 gene showed significant dysregulation in eight of 18 different tumor types from TCGA cohorts." (PMID 36774361, 2023). "Our analysis in this cohort found that FBXO44 was significantly associated with distant metastasis (χ2 = 6.19, P = 0.013) and advanced TNM stage (χ2 = 8.95, P = 0.030) of AEG tumor." (PMID 36774361, 2023). "The upregulation of FBXO44 protein in tumor samples was further validated in an independent clinical cohort of 251 AEG patients (P = 1.55E−4, Student’s t test)." (PMID 36774361, 2023). "The S-II subtype signature protein, FBXO44, is demonstrated to promote tumor progression and metastasis in vitro and in vivo." (PMID 36774361, 2023). "Furthermore, analysis of a tissue microarray (TMA) comprising 50 paired CRC samples (cohort 2) from our center demonstrated a marked elevation of FBXO44 protein levels in tumor tissues, supported by higher IHC scores in these samples." (PMID 41051444, 2025). "Conversely, FBXO44 overexpression accelerates tumor growth in vitro and in vivo." (PMID 41051444, 2025). "To evaluate the in vivo role of FBXO44, we commenced by generating xenograft tumor models." (PMID 41051444, 2025). "The results indicated that FBXO44 knockdown retarded the progression of CAC, as evidenced by enhanced body weight increase, decreased colon length, fewer tumor lesions, and less severe damage to colorectal tissues." (PMID 41051444, 2025). "We further assessed FBXO44 expression across a panel of CRC cell lines and observed that both protein and mRNA levels in NCM460 cells were significantly lower than in the tumor cell lines." (PMID 41051444, 2025). "Knockdown of FBXO44 inhibits CRC cell proliferation and organoid growth, as well as xenograft tumor growth and AOM/DSS‐induced intestinal tumorigenesis." (PMID 41051444, 2025). "In this model, logistic regression analyses demonstrated that clinical parameters (age, gender, and tumor stage) and core molecules (SLC2A1, TLE1, FAM83A, HMGA2, FBXO44, and MTRNR2L12) contributed differently to LUAD scores at different stages." (PMID 38338834, 2024). "We observed that FBXO44 OE increased the growth of AEG xenograft tumors by 2.54-fold (P = 0.004), whereas FBXO44 KD suppressed tumor growth by 67.17% (P = 0.029) in vivo." (PMID 36774361, 2023). "The FBXO44 protein exhibited significantly higher abundance in S-II AEG tumor samples than in S-II normal samples (P = 1.1E−4, Student’s t test), S-I tumor samples (P = 2.3E−3, Student’s t test), and S-III tumor samples (P = 5.3E−4, Student’s t test)." (PMID 36774361, 2023). "Targeting FBXO44 by genetic knockdown or pharmacologic inhibition of SUV39H1 restrained the proliferation of breast, lung, colon, and glioblastoma cancer cells in vitro and tumor growth in immunodeficient mice." (PMID 33681705, 2021).
FBXO44 also shares sentences with these, for which no sentence is quoted: cervical cancer (1 paper); cognitive decline (1); lung adenocarcinoma (1); stomach cancer (1).